EIF4E (eukaryotic translation initiation factor 4E)
Diseases named in the same sentence as EIF4E in open-access papers (continued):
Sharing a sentence is not in itself a finding about the gene and the disease.
breast carcinoma (continued). "EIF4E may be an important regulator of angiogenic factor (such as IL-8 and VEGF) production in breast cancer cells, affecting angiogenesis by regulating the translation of its target mRNAs (VEGF, Cyclin D1 and FGF2), and is associated with a poor prognosis in breast cancer." (PMID 36052258, 2022). "The HBXIP/lncRNA Hotair/LSD1 complex promotes the c-Myc-mediated transcription of cyclin A, eIF4E, and LDHA in the breast cancer cells." (PMID 34510316, 2022). "Eukaryotic translation initiation factor 4E (EIF4E) was a highly connected gene for Doxorubicin, and has been shown to promote tumor progression upon phosphorylation in breast cancer and lymphoma cells." (PMID 33413081, 2021). "Some cancers characterized by dysregulated eIF4E include acute myeloid leukemia (AML), multiple myeloma, diffuse large B-cell lymphoma, breast cancer, prostate cancer, head and neck cancer, and others." (PMID 34944805, 2021). "Consistent with our polysome fractionation experiments which show that eIF4E modulated protein synthesis of both ERα and FOXM1, the correlation between eIF4E with ERα and FOXM1 was verified in vivo using 134 Chinese breast cancer samples." (PMID 32066877, 2020). "In eIF4E overexpressing breast cancer, the increased ERα protein expression in turn enhances FOXM1 transcription, which together with its increased translation regulated by eIF4E, contributes to tamoxifen resistance." (PMID 32066877, 2020). "While confirming that eIF4E can govern the protein synthesis of ERα and FOXM1, in ER+ breast cancer, FOXM1 is a critical ERα target gene for modulating tamoxifen response." (PMID 32066877, 2020). "Our study uncovers a novel mechanism whereby phosphorylation independent eIF4E translational reprogramming in governing the protein synthesis of ERα and FOXM1 contributes to anti-estrogen insensitivity in ER+ breast cancer." (PMID 32066877, 2020). "Correspondingly, elevated expressions of eIF4E, p-4EBP1, and S6K1 correlated with breast cancer proliferation and survival." (PMID 31756179, 2019). "To explore the mechanism of delphinidin-induced autophagy, we examined the expression of the proteins in mTOR signalling pathway, including AKT, mTOR, eIF4e, and p70s6K, in HER-2 positive breast cancer cells." (PMID 29587684, 2018). "However, the role of eIF4E phosphorylation in breast cancer resistance to chemotherapy is unknown." (PMID 27926520, 2017). "Since the translation-dependent checkpoint mechanism remains undefined, we evaluated the impact of RPL24 depletion in a model human breast cancer cell line, SKBR3, sensitive to eIF4E-regulated and cap-dependent translation inhibition." (PMID 24970821, 2014). "Yang and colleagues recently reported that eIF4E levels were moderately correlated with VEGF and cyclin D1 in a breast cancer TMA." (PMID 19134194, 2009). "We found a significant correlation between the proportion of eIF4E-positive cells and MVD (p = 0.006, r = 0.34) in these breast cancer samples." (PMID 17010208, 2006). "Our findings suggest that eIF4E expression is closely related to IL-8 and VEGF expression in breast cancer cells, possibly contributing to disease progression." (PMID 17010208, 2006). "Using the Spearman rank correlation, significant correlations of eIF4E with both VEGF (p = 0.007, r = 0.316) and IL-8 (p = 0.007, r = 0.317) expression in breast cancer were noted." (PMID 17010208, 2006). "Immunohistochemical staining was used to determine protein expression of eIF4E, vascular endothelial growth factor (VEGF), interleukin-8 (IL-8), and CD105 in a set of 122 formalin-fixed, paraffin-embedded primary breast cancer tissues." (PMID 17010208, 2006). "Colony formation and CCK8 assays were performed to examine EIF4E overexpression and silencing effects on HER2‐negative breast cancer cell proliferation, and showed that EIF4E overexpression significantly enhanced colony formation and proliferation, while EIF4E knockdown markedly reduced levels." (PMID 40842081, 2025).
breast carcinoma (continued). "RNA interference system driven by the Survivin promoter efficiently and specifically downregulated eIF4E expression in human breast cancer cells but not in normal human breast epithelial cells." (PMID 37601696, 2023). "Breast cancer cell lines (MDA-MB-231, MDA-MB-468 and SKBR3) and a normal breast cell line (MCF-10A) were used to validate the expression levels of the signature m7GRGs (AGO2, EIF4E3, DCPS and EIF4E)." (PMID 37353728, 2023). "Taken together, these findings are supportive that the promotion of tamoxifen resistance in ER+ breast cancer through modulating the translation of the selective mRNAs mediated by eIF4E overexpression is independent of the phosphorylation status at S209." (PMID 32066877, 2020). "An earlier study also indicated that the expression of p-eIF4E, but not eIF4E, served as a predictor for survival in male breast cancer." (PMID 31756179, 2019). "In this study, the authors silenced the expression of eIF4E (experiment) in Tamoxifen-resistant breast cancer cells compared to a non-silencing control (control) using biological duplicates." (PMID 30409155, 2018). "Protective autophagy was induced over a range of treatment doses and was enhanced by an increase in the dose of delphinidin via suppression of the AKT/mTOR/eIF4e/p70s6k signalling pathway and activation of the LKB1/AMPK/ULK1/FOXO3a signalling pathway in HER-2 positive breast cancer cells." (PMID 29587684, 2018). "We found that breast cancer cells with overexpression of eIF4E S209D (Ser to Asp), but not S209A (Ser to Ala) significantly grow faster than control cells." (PMID 27926520, 2017). "To understand the function of eIF4E phosphorylation in cancer cells, we used retroviral transduction to establish breast cancer cell lines overexpressing the phosphor-mimetic form of eIF4E (eIF4E S209D) or the non-phosphorylatable form (eIF4E S209A)." (PMID 27926520, 2017). "This suggests eIF4E phosphorylation mainly plays a role in breast cancer cells’ response to chemotherapy rather than in disease development and progression." (PMID 27926520, 2017). "Here, we showed that compression induces miR-9 downregulation via DNMT3A-dependent promoter methylation, which leads to the upregulation of miR-9 target genes (LAMC2, ITGA6, and EIF4E) thus potentiating signal transduction for VEGFA expression in CAFs and breast cancer cells." (PMID 28252641, 2017). "Therefore, we investigated the physiological relevance of the collaborative regulation of eIF4E by cIAP1 and CHIP in breast cancer cell lines." (PMID 28852129, 2017). "Our work demonstrates that eIF4E phosphorylation is critically involved in chemoresistance and highlights the therapeutic potential of inhibiting MNK kinases to overcome resistance to chemotherapy in breast cancer patients." (PMID 27926520, 2017). "eIF4E gene is reported to be recognized as an proto-oncogene in vivo,and the extent of eIF4E overexpression can predict cancer recurrence and outcome in head neck squamous cell carcinoma (HNSCC), breast cancer and lung cancer." (PMID 24839543, 2014). "eIF4E protein expression is also elevated in a variety of human cancers including breast cancer but not in stroma or in benign tissue." (PMID 19134194, 2009). "The prognostic value of eIF4E has been reported earlier as independent of grade/nodal status in breast cancer; we have examined independence from the Nottingham Prognostic Index (NPI), which takes account of tumour size, grade and lymph node status." (PMID 19367274, 2009). "Combined with basal breast cancer markers CK 6 and Vimentin, the MAPK-signaling protein Erk1/2- pThr202/Tyr204 and the active mTOR signaling protein eIF4E-pSer209, these proteins could differentiate PAB resistant from PAB sensitive BC-PDMs (Mann Whitney U-test, ***p < 0.001)." (PMID 37596623, 2023). "In addition, we observed increased β-catenin activities in breast cancer cells overexpressing eIF4E S209D, but not S209A." (PMID 27926520, 2017).
breast carcinoma (continued). "Mnk has emerged as an exciting and promising strategy for cancer therapy, for example, degradation of Mnk1 blocks eIF4E phosphorylation and subsequently inhibits cell growth, colonization, invasion, migration and induces apoptosis in triple negative and HER2-overexpressing breast cancer cell lines." (PMID 27050281, 2016). "Successful ribavirin treatments in the breast cancer and refractory M4/M5 AML patients have attracted great interest along with attentions that ribavirin (eIF4E-targeted agents) treatment could be clinically beneficial in the 30% of cancers characterized by elevated eIF4E with poor prognosis." (PMID 26317515, 2015). "Although it has been reported that ribavirin has an effect on the types of breast cancer that overexpress eIF4E, eIF4E was not extracted and analyzed in the present study as eIF4E is upregulated in all high-grade astrocytic tumors and hence all malignant glioma cell lines." (PMID 25364409, 2014). "apMNKQ2 also inhibits eIF4E phosphorylation in breast cancer cells; however, in NSCLC cells, apMNKQ2 did not affect eIF4E phosphorylation, which is in accordance with other MNK inhibitors such as apMNK2F and apMNK3R aptamers or ferrocene analogs." (PMID 37111758, 2023). "But also identified signalling pathways not previously known to mediate progesterone action in breast cancer cells, such as MNK1/EIF4E pathway and the connection between CDK2, Cdc25 and the MAPK pathway." (PMID 36034422, 2022). "We found that eIF4E1 (also named eIF4E), but not eIF4E2, eIF4G1, eIF1A, eIF2α, or eIF5, is significantly increased in BCSCs, in comparison to SKBR-3, MCF-7 and MDA-MB-231 breast cancer cells and non-BCSCs of HMLER (CD44high/CD24low)SA cells." (PMID 25115391, 2014). "Because MNK kinases are required for eIF4E phosphorylation at S209 in tumors, but not normal cells, MNK inhibitors may provide a selective therapeutic approach to treating breast cancer." (PMID 27926520, 2017).
viral infection (45 papers, 2004 to 2025). "Eukaryotic initiation factors, such as eIF4E and eIF4G, function as host factors for viral infection, and loss-of-function mutations of these factors lead to virus resistance." (PMID 39985663, 2025). "In most plants, such as cucumber and tobacco, a single eIF4E allele is generally associated with the susceptibility to certain potyviruses, whereas in some plants, eIF(iso)4E mediates the resistance to viral infections." (PMID 39519021, 2024). "BaYMV adaptation to barley eIF4E-mediated resistance can be viewed as a two-component molecular ‘arms race’, for which viral infection is directly linked to the VPg-eIF4E interaction module." (PMID 35317071, 2022). "In this regard, it is noteworthy that the potyviral protein VPg, which is required for viral infection, interacts with eIF4E to induce infection; mutations in eIF4E." (PMID 34696360, 2021). "Previous studies of potyviruses suggest that mutations in the eIF4E/(iso)4E protein interrupt the interaction between viral genome-linked protein (VPg) and eIF4E/(iso)4E and confer plant resistance to virus infection." (PMID 34696530, 2021). "Eukaryotic translation initiation factors, including eIF4E, are susceptibility factors for viral infection in host plants." (PMID 33362728, 2020). "The eIF4E from plants was reported as a crucial host susceptibility component for viral infection and forms the largest group of recessive virus resistance genes in monocots and dicots." (PMID 30697226, 2018). "Before the discovery of RNA-guided RNA editing systems, the only way to combat the RNA viruses was to target the host susceptibility factors for viral infection such as the eukaryotic translation initiation factor 4E (eIF4E), eIF(iso)4E, and eIF4G." (PMID 30697226, 2018). "Interactions between eukaryotic translation initiation factors 4E (eIF4E) or its isoform eIF(iso)4E and the viral genome-linked protein (VPg) of potyviruses are required for the virus infection." (PMID 28167937, 2017). "Several resistance genes encoding a mutated form of eIF4E or eIF(iso)4E proteins have been shown to mediate resistance against viral infection in a range of plant/virus interactions." (PMID 28199446, 2017). "Fitting with this observation, viral infections known to cause dephosphorylation of eIF4E (e.g. vesicular stomatitis virus) result in a reduced polysomal loading of Nfkbia mRNA and activation of NF-κB, which leads to interferon production." (PMID 25561727, 2015). "The characterization of natural recessive resistance genes and Arabidopsis virus-resistant mutants have implicated translation initiation factors of the eIF4E and eIF4G families as susceptibility factors required for virus infection and resistance function." (PMID 20593023, 2010). "Although eIF4E proteins have emerged as the major mediators of the resistance to viral infections, the mechanism underlying the contributions of eIF4E to watermelon disease resistance remains unclear." (PMID 39519021, 2024). "Here, the expression of the movement protein and CMV movement may have been affected in the tomato plants carrying the edited alleles, although recent studies indicate that eIF4E is involved in multiple steps of various types of viral infection or propagation." (PMID 33362728, 2020). "Notably, fibroblasts and mice in which the serine at position 209 of eIF4E is replaced with alanine (low level of p-eIF4E) are less susceptible to virus infections, including HSV-1, VSV, and EMCV." (PMID 30388805, 2018). "Therefore, a physical interaction between wild type eIF4E (hereafter referred to as the susceptibility allele) and viral VPg is required for viral infection, and amino acid changes in the eIF4E protein encoded by the resistance allele impair binding with VPg and prevent infection." (PMID 22242134, 2011). "Several studies showed the manipulation of eIF4E and its regulatory cellular proteins during viral infections." (PMID 40733562, 2025).
viral infection (continued). "The viral protein genome-linked (VPg) has the ability to recruit plant translation initiation factors eIF4E, eIFiso4E, or both, to capture the host translational machinery and complete the virus infection cycle." (PMID 37446368, 2023). "The interaction between the viral protein genome (VPg) of potyviruses and the plant eIF4E is crucial for completing the virus infection cycle." (PMID 37446368, 2023). "It appears that the expression level of eIF4E is important for the establishment and maintenance of viral infection." (PMID 36016425, 2022). "It was reported that the Akt/mTOR pathway was required for eukaryotic translation initiation factor 4E (eIF4E) assembly and viral protein synthesis during virus infection." (PMID 35847100, 2022). "To study PVY-host interactions in these plants, we first analyzed changes in the level of expression of eIF4E upon viral infection." (PMID 31906869, 2020). "We have identified the interaction of UBCv1 with eIF4E through mass spectrometry and characterized that eIF4E increases its expression upon viral infection." (PMID 33384682, 2020). "Because of their essential role in viral infection, the eIF4E and eIF4G translation initiation factors (and isoforms) are coded by host genes hereafter referred to as susceptibility (S) genes." (PMID 31640557, 2019). "The VPg recruits the host eukaryotic translation initiation factor 4E (eIF4E), or its isoform eIF(iso)4E, in an interaction that is crucial for virus infection." (PMID 30978975, 2019). "The potyviral genome-linked protein (VPg) and the helper component proteinase (HCpro) interact with each other and with eIF4E and eIF(iso)4E and proteins are involved in the same functions during viral infection." (PMID 31847316, 2019). "Our preliminary results show that HHT antagonizes the level of phosphorylated eIF4E induced by viral infection." (PMID 30388805, 2018). "Phosphorylated eIF4E would rather favor the translation of selective mRNAs than impair translation initiation on a more global level upon viral infection." (PMID 30388805, 2018). "The knowledge regarding amino acid residues in eIF4E and VPg that are critical for virus infection can be utilized in the crop breeding programs as well as in the surveillance of emerging resistance-breaking virus variants." (PMID 27746794, 2016). "Various studies show how eIF4E and its regulatory cellular proteins are manipulated during viral infections." (PMID 25690796, 2015). "There is an alternate way for regulating eIF4E during viral infections by the direct interaction of this factor with different proteins coded by viruses." (PMID 25690796, 2015). "Phosphorylated forms of eIF4E also play a role in the translation of a subset of cellular mRNAs, including those involved in the response to viral infection." (PMID 24928504, 2014). "Because eIF4E transcript can be induced during virus infection, it is possible that ZmeIF4E transcript amounts would decline when less virus accumulates due to ZmELC silencing." (PMID 24954157, 2014). "Eukaryotic translation initiation factor 4E (eIF4E) plays an important role in plant virus infection as well as the regulation of gene translation." (PMID 23505421, 2013). "Previous results have shown that the physical interaction between eIF4E and VPg is necessary for viral infection and that some potyvirus strains are able to use several eIF4E proteins for infection." (PMID 22242134, 2011). "For example, eIF4E is a key player in the translation initiation by recruiting messenger RNAs to the ribosomal complex and has been repeatedly identified as an essential host factor for viral infection." (PMID 34454519, 2021). "Until recently, nCBP, another eIF4E isoform that is genetically distant to eIF4E and eIF(iso)4E, was not a susceptible factor for viral infection." (PMID 34454519, 2021).